LCN2 (lipocalin 2)
Diseases named in the same sentence as LCN2 in open-access papers (continued):
Sharing a sentence is not in itself a finding about the gene and the disease.
Chronic colitis (8 papers, 2016 to 2025). A chronic inflammatory disease of the large intestine (colon, cecum and rectum). "Lcn2 bone marrow chimeras was generated and evaluated for susceptibility to IL-10 receptor neutralization-induced chronic colitis." (PMID 27500193, 2016). "Interestingly, TiO2 NPs decreased the CD4+ T cells, T regs, and macrophages in the mesenteric lymph nodes and increased neutrophil gelatinase-associated lipocalin (LCN2) levels in mice aggravating the DSS-induced chronic colitis." (PMID 33669592, 2021). "Rag2−/− mice adoptively transferred with naïve T cells received daily oral gavage of PBS or CNP-miR146a for five consecutive days after they reached a predefined level of fecal lipocalin 2 (≥900 ng/g of fecal matter) as an indicator of established chronic colitis." (PMID 39771552, 2024). "Furthermore, prolapsed MHCIIΔIEC mice (MHCIIΔIEC*) demonstrated increased pathology consistent with chronic colitis, increased infiltration of myeloid cells, and elevated fecal lipocalin-2." (PMID 36602872, 2023). "As demonstrated in RT-PCR and Western blot, the expression levels of LCN2 in acute colitis, chronic colitis, and CAC were all higher than those of normal (P < 0.001), acute colitis was higher than that of the chronic colitis (P ≤ 0.01), and chronic colitis was higher than that of CAC (P < 0.05)." (PMID 35111677, 2021). "Experiments with bone marrow chimeric mice revealed that immune cells-derived Lcn2 are the major contributor in mediating protection against IL-10R neutralization-induced chronic colitis indicated by reduction in splenomegaly, colomegaly, shrunken ceca, MPO protein levels and activity." (PMID 27500193, 2016). "Moreover, we observed that LCN2 expression of chronic colitis could dramatically decrease compared with that of acute colitis (P < 0.05)." (PMID 35111677, 2021). "To dissect the relative contribution of immune and non-immune cells-derived Lcn2 in mediating protection against gut inflammation, we generated respective bone marrow chimera and evaluated their susceptibility to IL-10 receptor neutralization-induced chronic colitis." (PMID 27500193, 2016). "Indeed, we did not make a significant difference of LCN2 expression (P = 0.074) between chronic colitis and CAC in the tissue of animal model." (PMID 35111677, 2021). "However, the anti-inflammatory effects of strain ATCC were stronger than strain 139 in that ATCC significantly reduced spleen weight, colon inflammation index, and fecal lipocalin-2 content in mice with chronic colitis, while strain 139 was not." (PMID 31334133, 2019).
chronic liver failure (8 papers, 2016 to 2024). Liver failure that develops slowly and gradually for some time, possibly for years, often as the result of cirrhosis, or malnutrition. "Accordingly they studied LCN2 in plasma and urine as diagnostic marker of acute on top chronic liver failure (ACLF) in cirrhotic patients." (PMID 32856853, 2020). "Most interestingly, in this study it was demonstrated that the measurement of urine LCN2 had a better predictive power than the measurement of serum LCN2 in discriminating acute-on-chronic liver failure (ACLF) patients from cirrhotic patients with acute decompensation." (PMID 27729871, 2016). "However, a recent report showed that LCN2 in plasma and urine are both suitable as independent predictive factors of acute-on-chronic liver failure that correlates with liver failure and systemic inflammation." (PMID 27729871, 2016).
invasive breast carcinoma (8 papers, 2009 to 2023). A carcinoma that infiltrates the breast parenchyma. "Notably, other studies have proposed that the high cytoplasmic expression of LCN2 is associated with the decreased disease-free survival in patients with invasive breast cancer." (PMID 34072157, 2021). "However, there was a significant increase in Lcn-2 expression in patients with invasive ductal carcinoma (IDC), which is the most common type of invasive breast cancer, whereby a significant positive association was found between the disease severity score and Lcn-2 expression in serum." (PMID 37958332, 2023).
myeloma (8 papers, 2012 to 2024). "ChIP-on-chip data revealed that heparanase bound to regulatory regions of myeloma-related genes (i.e., CXCL12), encodes for SDF-1, CXCR4, CXCL2, CXCR3, CCL27, CX3CL1, and LCN2." (PMID 36980254, 2023). "RNA-sequencing analysis suggested communication between RUNX2, M-CSF, ITGB3, CD44, LCN2, and CLU in RUNX2 k/in myeloma cells." (PMID 36897488, 2023).
nasopharyngeal carcinoma (8 papers, 2020 to 2024). A carcinoma arising from the nasopharyngeal epithelium. "LCN2 is a biomarker associated with radioresistance and recurrence in nasopharyngeal carcinoma (NPC)." (PMID 38609844, 2024). "LCN2 was found to be highly expressed in the radioresistant nasopharyngeal carcinoma (NPC) cell line CNE2R, and there was a significant correlation between LCN2 expression and HIF-1α." (PMID 38778409, 2024). "Zhang et al10 showed that LCN2 was a potential biomarker for radioresistance and recurrence in nasopharyngeal carcinoma." (PMID 37089051, 2023). "Here, we used a bioinformatic analysis of a nasopharyngeal carcinoma database to support the finding that LCN2 reduced MET levels to inhibit nasopharyngeal cancer cell migration." (PMID 36428800, 2022). "However, the molecular mechanisms involved in the LCN2-mediated cancer metastasis of human nasopharyngeal carcinoma remain poorly understood." (PMID 36428800, 2022). "In nasopharyngeal carcinoma (NPC), LCN2 was highly expressed in the radioresistant NPC cell line CNE2R." (PMID 39188682, 2024).
brain injury (7 papers, 2015 to 2025). Acute and chronic (see also brain INJURIES, CHRONIC) injuries to the brain, including the cerebral hemispheres, CEREBELLUM, and brain STEM. "Despite several studies on the effects of LCN2 on memory impairment in various brain injuries, the response of LCN2 to AβO has been less studied in vivo models." (PMID 34829528, 2021). "In response to a variety of brain injuries, LCN2 protein is secreted extracellularly, where it can be pharmacologically targeted by therapeutic antibodies and inhibitors." (PMID 33421207, 2021). "LCN2 secretion was activated during brain injuries and it was negatively regulated by miR-138-5p." (PMID 31485266, 2019).
dermatitis (7 papers, 2016 to 2025). An inflammatory process affecting the skin. "Th17 cell-associated genes, (i.e., S100a8, CAMP, BATF, IL-23A, LCN2, and HIF-1α) highly expressed in Nfkbiz−/− mice with dermatitis, were downregulated after antibiotic treatments." (PMID 28740238, 2017). "Furthermore, IL-17A target genes (i.e., S100a9, S100a8, CAMP, and LCN2) were remarkably upregulated in the skin of Nfkbiz−/− mice with dermatitis." (PMID 28740238, 2017). "However, in this study, we observed robust Th17 responses as well as expression of IL-17A signature genes (i.e., S100a8, S100a9, CAMP, and LCN2) in the skin of Nfkbiz−/− mice with spontaneous dermatitis." (PMID 28740238, 2017).
glaucoma (7 papers, 2021 to 2025). Increased pressure in the eyeball due to obstruction of the outflow of aqueous humor. "For each of the 4 clusters, notable genes associated with glaucoma, neuroinflammation, or reactive astrocytes were: Cluster 1 (Nrf2, Hspb1, S100β), Cluster 2 (Ptgs2, Clcf1), and Cluster 4 (C2, Tlr4, Lcn2, H2-T23, Thbs1, Il6ra)." (PMID 37759301, 2023). "This evidence has guiding significance for future exploration of the source of elevated LCN2 levels in peripheral blood following acute glaucoma injury." (PMID 40083945, 2025). "In the future, it is imperative to analyze the cellular source of the elevated LCN2 in serum after acute glaucoma injury through comprehensive serum testing." (PMID 40083945, 2025). "High levels of lipocalin 2 (LCN2), a neutrophil protein, presents in the aqueous humor of glaucoma patients and RGCs of glaucoma animal models." (PMID 38502592, 2024). "Various studies using whole transcriptome analyses in rodent glaucoma models have indicated that LCN2 is upregulated in glaucomatous retinae." (PMID 39125762, 2024). "The three hub genes SERPINA3, IL1R1, and LCN2 were validated as potential diagnostic biomarkers through real-time PCR, showing increased expression in the OGD/R-induced glaucoma model." (PMID 39125762, 2024). "Astrocytes are thought to be the primary source of Lcn2 in the brain and its up regulation has been noted in the retina secondary to glaucoma, implicating it in the promotion of neuroinflammation in the disease." (PMID 37759301, 2023). "Several reports of whole transcriptome analyses in rodent glaucoma models have revealed that Lcn2 is upregulated in glaucomatous retinae." (PMID 34136483, 2021). "Moreover, three hub genes, SERPINA3, IL1R1, and LCN2, were validated as potential diagnostic biomarkers for high-risk glaucoma patients, showing increased expression in the OGD/R-induced glaucoma model." (PMID 39125762, 2024). "Moreover, the involvement of lipocalin 2 was confirmed in two in vivo models of glaucoma, spontaneous glaucomatous DBA/2J mice, and in a model of mice with an optic nerve crush (OCN) injury, respectively." (PMID 39458974, 2024). "Very few glaucoma-related neuroinflammatory and reactive astrocyte genes and pathways were differentially expressed (Hsp70, Hsp90, Hspb1, C2, Tlr4, S100b, Lcn2, H2-T23), and understanding their significance to an overall neuroinflammatory astrocyte requires more focused functional testing." (PMID 37759301, 2023). "Lipocalin 2 (Lcn2) is upregulated in glaucomatous retinae; however, whether Lcn2 is directly involved in glaucoma is debated." (PMID 34136483, 2021). "LCN2 has the potential to serve as a candidate biomarker for predicting the severity of the neuroinflammatory response following acute glaucoma, which may provide new evidence to retinal repair strategies for better visual function recovery at intervention time points and new targets." (PMID 40083945, 2025). "Furthermore, Feng and Xu suggested LCN2 as a biomarker for glaucoma." (PMID 38502592, 2024). "However, to our knowledge, the direct involvement of Lcn2 in glaucoma caused by ocular hypertension has not been investigated." (PMID 34136483, 2021). "Our study identified and validated six neuroinflammation-related hub genes in glaucoma (SERPINA3, LCN2, MMP3, S100A9, IL1RN, and HP)." (PMID 39125762, 2024). "Our findings revealed a significant decrease in the mRNA levels of SA1009 and MMP3 in the glaucoma model group compared to the normal group, while SERPINA3, IL1RN, and LCN2 expression increased." (PMID 39125762, 2024). "Whether iron dysregulation occurred within the pressure-treated retinae in our system and how this relates to Lcn2 upregulation should be determined in future studies, alongside investigations into the potential therapeutic application of iron chelators in the treatment of glaucoma." (PMID 34136483, 2021).
lung diseases (7 papers, 2015 to 2025). "From our analyses and previous literatures, we focused on Lcn2, S100a9 and S100a8 as potential genes that may play a key role in indium-induced lung diseases." (PMID 39516272, 2025).
malnutrition (7 papers, 2015 to 2024). Inadequate nutrition resulting from poor diet, malabsorption, or abnormal nutrient distribution. "Simultaneous, quantitative MPO, FL, FC and Lcn-2, levels were determined in frozen fecal specimens collected from 78 children (mean age 15.2 ± 5.3 months) in a case-control study of childhood malnutrition in Brazil." (PMID 27746954, 2016). "MAL dams developed mild signs of colon inflammation, quantified as colon shortening, and increased fecal lipocalin-2 (LCN-2) levels, suggesting malnutrition affected both the small intestine and the colon structure." (PMID 38959887, 2024). "We have previously demonstrated the tight correlation of fecal biomarkers lipocalin-2 (LCN-2) and myeloperoxidase (MPO) with malnutrition and disease burden in the MAL-ED study in children." (PMID 29661930, 2018).
memory impairment (7 papers, 2021 to 2024). "Despite these limitations, this study indicates that LCN2 and iron are involved in sustained glial activation, and that activated glial cells play a role in AβO-induced memory impairment via neuroinflammation, iron-related oxidative stress, and BBB disruption." (PMID 34829528, 2021). "Lipocalin 2-null mice demonstrate not only anxious and depressive-like behaviors, but also cognitive and memory impairments." (PMID 35010945, 2021). "Recent research on the influence of LCN2 on memory impairment found that LCN2 is engaged in cellular mechanisms of Aβ42-induced neuroinflammation and the proapoptotic signaling pathway, according to in vitro studies." (PMID 34829528, 2021). "Lipocalin 2-null mice are reported to display anxious and depressive-like behaviors, as well as cognitive and memory impairment." (PMID 34565419, 2021). "Similarly, a recent study showed that rodents receiving exogenous LCN2 displayed hippocampal neuronal dysfunction and memory impairment." (PMID 35281301, 2022). "Interestingly, peripheral LCN2 was shown to be associated with executive dysfunction in preclinical and mild AD patients rather than with memory impairment, which is the typical early symptom of AD-related pathology." (PMID 35027079, 2022). "However, both models showed increased LCN2 and iron accumulation, suggesting that this pathway may be a primary mechanism of memory impairment." (PMID 34829528, 2021).
pancreatitis (7 papers, 2007 to 2025). Inflammation of the pancreas. "Six transcripts encoding inflammation-related proteins were found to be upregulated by activation of LEPRb, namely lipocalin-2, pancreatitis-associated protein, preprotachykinin-1, fibrinogen-β, tissue-type plasminogen activator (tPA) and manganese-dependent superoxide dismutase (MnSOD)." (PMID 17521427, 2007). "In 2013 a study had strongly suggested LCN2 in the alkaline pancreatic juice as a marker for differentiating diseased from non-diseased pancreas and that LCN2 could contribute to understanding the etiology of pancreatitis." (PMID 27729871, 2016). "Pharmacological or genetic blockade of the NUPR1-LCN2 pathway (using NUPR1 shRNA, LCN2 shRNA, pancreas-specific Lcn2 conditional knockout mice, or the small molecule ZZW-115) increases the activity of the ferroptosis inducer erastin and worsens pancreatitis, in suitable mouse models." (PMID 33510144, 2021).
pyelonephritis (7 papers, 2016 to 2025). An inflammatory process affecting the kidney. "For example, the decrease in PCs after Li treatment results in polyuria since PCs regulate water balance, while the decrease in ICs by Tfcp2l1 deletion enhances kidney infection since ICs mediate urinary acidification and the production of a number of antimicrobials including Lcn2/NGAL." (PMID 28577314, 2017).
acute appendicitis (6 papers, 2016 to 2023). "We hypothesized that there could be a link between appendicitis and neutrophil gelatinase-associated lipocalin (NGAL) = lipocalin 2 (LCN2) = siderocalin because appendicitis is inflammation of the appendix: the inflamed appendix becomes infected with intestinal bacteria." (PMID 27026889, 2016).
diabetic encephalopathy (6 papers, 2019 to 2024). A brain disease that is characterized by functional impairment of cognition, cerebral signal conduction, neurotransmission and synaptic plasticity, and underlying structural pathology associated with diabetes. "This supports the notion that LCN2 deficiency reduces levels of reactive gliosis and inflammatory cytokines in mice with diabetic encephalopathy." (PMID 38201988, 2024). "Taken together, specific mechanisms relating to the association between LCN2 and IR in the brain can be additional factors aggravating diabetic encephalopathy." (PMID 33613327, 2021). "Therefore, we strongly suggest that both LCN2 and TonEBP are systemic inflammatory mediators that play a causative role in diabetic encephalopathy." (PMID 34844610, 2021). "Our results suggest that LCN2 may contribute to the augmentation of hippocampal inflammation and subsequent pathologies associated with diabetic encephalopathy." (PMID 30761088, 2019). "Moreover, LCN2 deficiency significantly reduced gliosis, the recruitment of macrophages, and the production of inflammatory cytokines in diabetic mice, suggesting a critical role of LCN2 in the pathogenesis of diabetic encephalopathy." (PMID 37371057, 2023). "In accordance with evidence that hippocampal LCN2 levels are increased in diabetic encephalopathy, we found that serum and hippocampal LCN2 levels were elevated in HFD-fed mice and normalized by IF." (PMID 38201988, 2024). "Taken together, we suggest, for the first time, that under diabetic conditions, elevated LCN2 and TonEBP in inflammatory cells adversely influence diabetic encephalopathy through BBB leakage." (PMID 34844610, 2021). "Taken together, our findings highlight the critical role of LCN2 in the pathogenesis of diabetic encephalopathy." (PMID 30761088, 2019). "The extent to which it can worsen cognitive ability in diabetic mice makes LCN2 a promising target for therapeutic interventions against diabetic encephalopathy." (PMID 30761088, 2019). "We used the HDS model to explore molecular changes and to identify the role of LCN2 in the pathogenesis of diabetic encephalopathy." (PMID 30761088, 2019). "Therefore, our results suggest that IF provides neuroprotection against the aggravating neuroinflammatory response in diabetic encephalopathy by downregulating astrocytic LCN2 and microglial GAL3 levels." (PMID 38201988, 2024). "In diabetic encephalopathy, elevated LCN2 promotes neuroinflammation and oxidative stress." (PMID 35884685, 2022). "Based on these results, the functional regulation of LCN2 as a proinflammatory factor in the progression of diabetic encephalopathy could be regulated by TonEBP." (PMID 34844610, 2021). "Therefore, further functional regulation of LCN2 in the progression of diabetic encephalopathy is necessary." (PMID 34844610, 2021). "Taken together, these findings indicate that under chronic diabetic conditions, both LCN2 and TonEBP may play crucial roles as mediators of diabetic encephalopathy." (PMID 34844610, 2021). "Based on these observations, we hypothesized that LCN2 might play an important role in the development of diabetic encephalopathy." (PMID 30761088, 2019).
diabetic retinopathy (6 papers, 2023 to 2026). "Three secreted angiogenic factors-Fgf2, Pgf, and Lcn2-known to contribute to diabetic retinopathy, were induced." (PMID 42103933, 2026). "This study showed that Kdm6a in microglia/macrophages aggravates diabetic retinopathy by increasing lipocalin 2 (LCN2), which impairs glycolysis in photoreceptor cells." (PMID 38454477, 2024). "Endothelial Lcn2 was upregulated in diabetic retinal injury and Lcn2 silencing attenuated diabetic retinopathy progression." (PMID 37222464, 2023). "On the other hand, downregulation of LCN2 was shown to significantly inhibit cell migration, invasion, angiopoiesis, and pyroptosis regulated by caspase-1, thus attenuating the progression of diabetic retinopathy." (PMID 37371057, 2023).